CASP1 (caspase 1)
Diseases named in the same sentence as CASP1 in open-access papers (continued):
Sharing a sentence is not in itself a finding about the gene and the disease.
Sepsis (continued). "While S1PR2 signaling was implicated in caspase-11–dependent macrophage pyroptosis in one sepsis model, others found CC1 regulated LPS-driven NLRP inflammasome and caspase-1 activation." (PMID 36719377, 2023). "YTHDF1 alleviated sepsis by upregulating the transcription of WWP1 to induce NLRP3 ubiquitination and inhibit caspase-1-dependent pyroptosis." (PMID 38022612, 2023). "As we have verified that SJS is able to modulate pyroptosis in sepsis animal model, next, we detected the protein level of GSDMD, and caspase-1 of MH-S cells treated with LPS and ATP along with different concentrations of SJS." (PMID 37062835, 2023). "In this study, the protein levels of NLRP3, Caspase 1 p20, and IL‐1β in the myocardium of mice from the NR1H3‐KO + CLP group were significantly higher than those from the WT + CLP group, suggesting that NR1H3 deficiency could lead to activation of NLRP3 signaling pathways during sepsis." (PMID 37206244, 2023). "Based on the RFWK inhibitory motif, we designed an RFWK peptide inhibitor to target caspase-1/11 activity and found the inhibitor substantially suppresses GSDMD cleavage and IL-1β release, as well as LPS-induced sepsis in mice." (PMID 36322773, 2022). "The expression of NLRP3, Caspase-1, GSDMD, IL-1β, and IL-18 was decreased, suggesting that ALDH2 also inhibited pyroptosis in sepsis-induced lung injury." (PMID 35188436, 2022). "Of note, the upregulation of NLRP3, cleaved caspase-1 and cleaved GSDMD that are related to caspase-1-dependent pyroptosis was found in pneumonia-induced sepsis." (PMID 35508474, 2022). "NLRP3, caspase-1, and ASC have been exploited as new therapeutic targets against pyroptosis and sepsis." (PMID 36077522, 2022). "Sepsis-exos also decreased the expression of HMBOX1 but increased the levels of NLRP3, active caspase-1, pro-caspase-1, and GSDMD-N." (PMID 35345489, 2022). "Since the immune response during sepsis is partly mediated by caspase-1 and -11 induced GSDMD-pyroptosis, we used the Casp1/11-/- mice to study gasdermin expression during sepsis." (PMID 34996441, 2022). "We found LPS-related sepsis visibly upregulated the mRNA expression of IL-6, TNF-α, pyrocytosis-related factors (such as caspase-1), hypoxia-inducible factors (such as HIF1-α), and chemokines." (PMID 35156512, 2022). "We showed that sepsis-exo or miR-885-5p mimic not only elevated IL-1β and IL-18, but also increased NLRP3, caspase-1, and GSDMD-N, leading to promotion of pyroptosis." (PMID 35345489, 2022). "In addition, NET-derived HMGB1 causes caspase-1 activation and later macrophage pyroptosis through receptor for advanced glycation end products (RAGE) and dynamic-dependent signaling, in which histones play a key role, augmenting inflammatory responses following sepsis." (PMID 36059483, 2022). "Previous studies have demonstrated that NETs can induce macrophage pyroptosis, elevate caspase-1 with increasing NETs dose, and increase inflammatory cytokines IL-1β and TNF-α in sepsis." (PMID 36430491, 2022). "We report here that experimental sepsis led to an overactivation of the NLRP3 complex and consequent activation of its downstream mediator caspase-1, which were significantly reduced by treatment with ICOS-Fc, thus leading to reduced systemic release of IL-1β." (PMID 36119089, 2022). "During the outbreak period, research on pyroptosis in sepsis proliferated, which showed 4/5/11 can bind LPS produced by intracellular bacteria without the need for other intracellular receptors, which can directly activate caspase-11 without the action of caspase-1 and then cause pyroptosis." (PMID 36032662, 2022). "To conclude, the regulatory role of WWP1 in sepsis was achieved through its mediation of NLRP3 inflammasomes and caspase-1-dependent pyroptosis." (PMID 35508474, 2022). "Via reducing PKR phosphorylation and caspase-1 activity, both PKM2 inhibitors (shikonin) and PKR inhibitors (C16) were capable to protect mice from lethal sepsis." (PMID 34824200, 2021).
Sepsis (continued). "These events hamper the binding of pro-caspase-1 to ASC, inhibiting NLRP3 inflammasome activation and alleviating LPS-induced sepsis injury in mice." (PMID 34305952, 2021). "In polymicrobial sepsis induced by cecal ligation and puncture (CLP), inhibiting the activity of CASP1 with the NLRP3 inhibitor MCC950 also reduces platelet activation in rats." (PMID 33796108, 2021). "Compared to the Sepsis-C group, the Sepsis-G group had higher liver caspase-11 and NLRP3 gene expressions at 24 h and lower active caspase-1/11 and cleaved GadD protein levels at 72 h after sepsis." (PMID 32295272, 2020). "The downregulated expressions of caspase-1/11 and GadD in the late phase (72 h post-CLP) in the GLN sepsis group cannot be explained by immunosuppression." (PMID 32295272, 2020). "In this study, we found that caspase-1 and caspase-11 gene expressions in the liver post-CLP were both upregulated, indicating that pyroptosis occurred after sepsis." (PMID 32295272, 2020). "Our study demonstrated that the activation levels of NF-κB (p65), pro-caspase-1, pro-IL-1β, NLRP3, caspase-1 and IL-1β were increased after CLP/LPS+ATP, illustrating that the NLRP3/caspase-1/IL-1β signaling pathway participates in sepsis." (PMID 30779706, 2019). "Caspase-1-mediated GSDMD cleavage was consequently decreased, which prevented pyroptosis in LPS-induced sepsis in mice." (PMID 31189875, 2019). "Myocardial mRNA levels of IL-1β, IL-6, IL-18, IP-10, E-selectin and PAI-1 were significantly elevated in RV and LV during sepsis compared to PAB, while Caspase-1 was decreased in septic compared to PAB animals (all p<0.05)." (PMID 31247004, 2019). "Most importantly, MCC950 or Ac-YVAD-CMK treatment prevented sepsis-induced neuronal damage and cognitive deficits in CLP mice, suggesting that the NLRP3/caspase-1 pathway is involved in the neurotoxicity and cognitive impairments observed in SAE." (PMID 30276509, 2019). "Caspase 1 activity and secretion of IL‐1β by platelets were assessed to confirm activation of the NLRP3 inflammasome in platelets after induction of sepsis in CLP rats." (PMID 31054188, 2019). "In addition to the processing of IL-1β, caspase-1 may execute apoptosisduring sepsis." (PMID 25412304, 2014). "Thus, caspase-1 could be an effective target for the treatment of sepsis." (PMID 24454930, 2014). "Several mediators such as activated protein C, Caspase 1, Caspase 3, and ICAM-1 do play a pivotal role in animal models of sepsis-induced acute kidney injury." (PMID 19486524, 2009). "Furthermore, both in vivo and in vitro experiments demonstrated that XQHF modulates sepsis-induced acute lung injury, at least in part, through the inhibition of the NLRP3/Caspase-1-dependent pyroptosis signaling pathway." (PMID 41710028, 2026). "In light of the previously published results, the current study evaluated if CLM might prevent liver damage brought on by sepsis, for the first time, by preventing NLRP-3/Caspase-1 pathway-mediated pyroptotic cell death in rats." (PMID 40770673, 2025). "While the secreted caspase-1 was not significantly different from that of p62 (p>0.05) in Sepsis Alone cohort, secreted MLKL was significantly higher than that of caspase-1 (> 6-fold increase, ***p=0.0004) and p62 (> 7-fold increase, ***p=0.0002)." (PMID 40051620, 2025). "Experimental models have demonstrated that genetic ablation of inflammasome components—such as NLRP3, caspase-1, caspase-11, or GSDMD—confers protection against sepsis-induced mortality by attenuating systemic inflammation, coagulopathy, and multiorgan dysfunction." (PMID 40558557, 2025). "Hence, ADAM17, CASP1, CD81, and MGMT are likely to be potential core targets in Calculus Bovis treatment for sepsis." (PMID 40258762, 2025). "Intracellular caspase-1 significantly increased in the C19wSepsis and Sepsis Alone cohorts, with no significant increase in the C19NoSepsis cohort compared to controls." (PMID 40051620, 2025).
Sepsis (continued). "The protein levels of pyroptosis markers, including NLRP3, caspase-1 p20 and GSDMD-N, were suppressed by BRD3308, which indicated that BRD3308 may alleviate sepsis-induced ALI by inhibiting pyroptosis in macrophages." (PMID 39224841, 2024). "Building on this previous work, our study identified caspase-1 and Aβx-40 as indicators of sepsis and end organ injury, respectively, independent of pathogen." (PMID 38410714, 2024). "Plasma caspase-1 levels displayed the best predictive value in discriminating ICU patients with sepsis from non-infected ICU patients (area under the receiver operating characteristic curve=0.7080)." (PMID 38410714, 2024). "C57BL/6 background-derived Casp11−/− mice were found to resist high doses of LPS, while Casp1−/− mice with only the Casp1 deficiency could not resist LPS, indicating that the LPS-induced activation of the Casp11 signaling pathway plays a crucial role in sepsis pathology." (PMID 37681852, 2023). "VX-765, a selective caspase 1 inhibitor, reduces activation and activity of caspase 1 and antagonizes NLRP3 inflammasome assembly and activation in the context of several inflammatory disorders and diseases such as atherosclerosis, sepsis, or alzheimer disease." (PMID 36800238, 2023). "Further, our findings are consistent with other studies showing an increased level of active CASP1 but decreased quantity of active CASP3 in patients who survived sepsis compared with non-survivors." (PMID 38022511, 2023). "Furthermore, an RFWK motif-based peptide inhibitor can inhibit caspase-1/11 activation and its downstream substrates GSDMD and interleukin-1β cleavage, as well as lipopolysaccharide-induced sepsis in mice." (PMID 36322773, 2022). "The data showed a marked upregulation in the expression levels of TXNIP, NLRP3, caspase-1, and IL-1β, suggesting that the NLRP3 inflammasome may contribute to liver dysfunction during sepsis." (PMID 35136484, 2022). "The expression of key inflammasome proteins NLRP3 and caspase-1 and pyroptosis-related proteins GSDMD, IL-1β, and IL-18 was decreased, suggesting that inhibition of pyroptosis also alleviated lung injury in mice with sepsis." (PMID 35188436, 2022). "In DEFA1/DEFA3 transgenic mice, increased gene copy numbers of DEFA1/DEFA3 worsen sepsis by inducing endothelial pyroptosis and vascular permeability in a canonical Nod-like receptor family pyrin domain containing 3 (NLRP3)/caspase-1 inflammasome dependent manner." (PMID 35935811, 2022). "The present study showed that TXNIP knockdown significantly inhibited hippocampal microglia activation in the sepsis mice, while the NLRP3 and cleaved caspase-1 protein expression levels and the inflammatory factors, IL-1β and IL-18, were significantly reduced in the hippocampus." (PMID 35571246, 2022). "The elevated secretion of IL-1β and IL-18, and expression pattern of HMBOX1, NF-κB (cytoplasm), nuclear NF-κB, NLRP3, caspase-1, and GSDMD-N were all reversed by overexpression of HMBOX1, showing that sepsis-exos and miR-885-5p mimic had similar effects on AC16 cells." (PMID 35345489, 2022). "The western blot showed that CLP-induced sepsis promoted GSDMD, caspase-1, and NLRP3 expression." (PMID 35979014, 2022). "Moreover, levels of HMBOX1 in heart tissues were dramatically decreased, while expression of pyroptosis-related proteins NLRP3, caspase-1, and GSDMD-N were all upregulated after treatment of sepsis-exos." (PMID 35345489, 2022). "Paradoxically, here we discovered that although disruption of caspase-1/11 aggravated C. albicans infection as previously reported, disruption of GSDMD, an effector molecule downstream of caspase-1/11, protected against C. albicans-induced sepsis." (PMID 34795266, 2021). "Blood assays revealed that when primed with the TLR3 agonist poly(I:C), LPS-induced coagulation factor III (F3) release and lethal coagulation in mice suffering from sepsis required CASP11 but not CASP1-mediated GSDMD activation." (PMID 34858408, 2021).
Sepsis (continued). "Our findings indicated that the expression of ERS components (GRP78, ATF4, and CHOP) was significantly upregulated in DCs after the initiation of sepsis, showing the same tend as inflammasome activation, hinting at a relationship between PERK–ATF4–CHOP signaling and CASP-1-mediated pyroptosis." (PMID 34741186, 2021). "GPX4 was found to negatively regulate Gasdermin D-mediated pyroptosis in lethal polymicrobial sepsis by reducing lipid peroxidation; in contrast, conditional GPX4 knockdown in myeloid cells triggers macrophage pyroptosis with caspase-1/caspase-11-GSDMD-phospholipase C gamma 1 axis." (PMID 34899864, 2021). "Although we observed a relatively high activity of caspase-1 in sham mice, sepsis did not increase it further, and there was no significant increase in IL-1β in the BM." (PMID 34367170, 2021). "Mice lacking key inflammasome components such as NLRP3 or caspase-1/11 are more resistant to polymicrobial and LPS-induced sepsis than wild-type mice and are less likely to die from lethal endotoxemia." (PMID 34795266, 2021). "In addition, it has been reported that NETs promote peritoneal macrophage pyroptosis, a caspase-1-dependent regulated cell death, and the production of macrophage-derived Il-1β and TNF-α32 in sepsis." (PMID 33214582, 2020). "And it was found that estrogen administration could dramatically reverse sepsis-induced up-regulation of cleaved GSDMD and caspase-1 as well as NLRP3." (PMID 33002070, 2020). "In summary, our data suggest the NLRP3/caspase-1 signaling pathway may play a vital role in neuronal pyroptosis and cognitive impairments in the development of SAE secondary to a sepsis." (PMID 30276509, 2019). "On the other hand, blockade of pyroptosis by caspase-1/-11 or gasdermin D gene deletion renders mice resistant to endotoxin-induced sepsis, suggesting NLRP3 and other inflammasome activation play a critical role in sepsis." (PMID 29375379, 2017). "The present study demonstrates that GIK protects intestinal mucosal barrier function in CLP-induced sepsis and that UCP2 and the NLRP3/caspase-1/IL-1β signaling pathway may be involved in this process." (PMID 28428961, 2017). "Consistent with this concept, mice with caspase-1/-11 or gasdermin D gene deletion, thus lacking inflammasome activation and pyroptosis, are resistant to endotoxin-induced sepsis." (PMID 27812336, 2016). "Previous studies from our laboratory have demonstrated that caspase-1 does induce apoptosis during murine models of sepsis and that the apoptotic function is independent of its IL-1β and IL-18 processing function." (PMID 24643116, 2014). "To account for this, we modeled the predictive ability of the MV caspase-1 activity for determining sepsis with and without inclusion of the severity of illness score." (PMID 24643116, 2014). "We demonstrated that active caspase-1 which cleaves pro-IL-1β into bioactive IL-1β, was nearly absent in patients with sepsis or in volunteers receiving an LPS infusion." (PMID 21244670, 2011). "Additionally, LL-37 has been shown to alleviate sepsis-induced acute lung injury by downregulating the expression of key components of the pyroptotic pathway, including NLRP3, caspase-1, and GSDMD, as well as downstream inflammatory factors in alveolar epithelial cells." (PMID 40072070, 2025). "Additionally, pharmacological inhibition of the NLRP3-caspase-1 inflammasome has demonstrated a reduction in the expression of both GSDMD and its cleavage form, GSDMD-N, effectively mitigating pyroptosis in the mouse brain following sepsis." (PMID 38627764, 2024). "Furthermore, immunofluorescence staining demonstrated co-localization of the pyroptosis markers Caspase-1 and NLRP3 with the macrophage-specific antibody F4/80, providing further evidence that sepsis-induced lung injury can be prevented by inhibiting macrophage pyrolysis by GDF3." (PMID 38543054, 2024). "Additionally, the roles of targets such as CASP1/3, BCL2, and MTOR in sepsis have been discussed." (PMID 39584444, 2024).
Sepsis (continued). "Studies have shown that inhibiting caspase-1 can protect the ultrastructure of the brain, particularly the blood-brain barrier, and significantly reduce apoptosis and the release of inflammatory cytokines, thereby preserving cognitive function in CLP-induced experimental sepsis mice." (PMID 39027435, 2024). "Once formed, the NLRP3 inflammasome activates caspase-1, which subsequently mediates the cleavage of pro-IL-1β and pro-IL-18 and the secretion of their bioactive forms, important players in the systemic inflammation and cardiac dysfunction (and MOF) during sepsis." (PMID 39559354, 2024). "Indeed, Aβx-40 and caspase-1 were significantly correlated in ICU-sepsis patients but not in the healthy control or ICU-non-sepsis groups." (PMID 38410714, 2024). "Caspase-1 plasma levels were not significantly different in either the sepsis or non-sepsis cohorts, whereas Aβx-40 and Aβx-42 plasma levels significantly increased from time of admission to 7dp in the sepsis cohort." (PMID 38410714, 2024). "Highlighting this concept of variance, the data presented herein demonstrate that caspase-1 was significantly elevated and skewed towards the higher end in both ICU cohorts compared to healthy controls, and its plasma levels were a highly reliable indicator of sepsis as a primary outcome." (PMID 38410714, 2024). "Thus, circulating monocyte EV caspase-1 may induce vascular injury and contribute to ARDS development during sepsis." (PMID 37180111, 2023). "Moreover, differences in the expression of CASP1, CASP3, CASP4, and CASP5 could help distinguish the level of immune cell infiltration in sepsis." (PMID 37939116, 2023). "Moreover, western blot analysis in the liver tissues found that administration of a high dose of HNP-1 after sepsis onset activated caspase-1 in all tested mice, while administration of a low dose of HNP-1 after sepsis onset only activated caspase-1 in part of mice." (PMID 35935811, 2022). "A recent study also showed that the caspase-1 inhibition dramatically downregulated the pyroptosis, reduced the release of the inflammatory cytokines, protected the ultrastructure of the brain, and preserved the cognitive functions in the CLP-induced experimental sepsis." (PMID 35571246, 2022). "Several sepsis studies investigate the interaction of melatonin with NLRP3 in mouse hearts, where sepsis activates the NLRP3 inflammasome and melatonin injection suppresses this activity, confirmed by a decrease in the levels of mature caspase-1 and IL-1β, NLRP3, and ASC." (PMID 34202842, 2021). "Gsdmd deletion, without affecting the cleavage and activation of caspase 1, conferred partial protection from C. albicans-induced sepsis and disease, as shown by increased survival, alleviation of infection-induced body weight loss, and improved clinical outcomes in Gsdmd-/- mice." (PMID 34795266, 2021). "Moreover, we demonstrated that treatment of septic mice with CitH3 monoclonal antibody significantly improves survival and sepsis-ALI in a murine model of CLP-induced septic shock, likely due to inhibition of CitH3 activated Caspase-1 dependent inflammasome pathway." (PMID 34950139, 2021). "Since caspase-1/11 activation initiates pyroptosis, which promotes the recruitment of phagocytes, pretreating mice with GLN may enhance bacterial clearance at an earlier phase of sepsis (24 h post-CLP)." (PMID 32295272, 2020). "The significance of microvesicular caspase-1 activity persisted adjusting for severity of illness with the change in the point estimate of <10% indicating that the elevated caspase-1 activity seen was specific to sepsis and not due to the overall severity of illness of a patient." (PMID 24643116, 2014). "However, during sepsis progression, if the UPR cannot reestablish cellular equilibrium, the endoplasmic reticulum stress (ERS) response shifts to a proapoptotic mode; the key nuclear caspase-1, which recognizes and processes gasdermin-D (GSDMD), is upregulated, leading to pyroptosis." (PMID 40153575, 2025).